EGFR (epidermal growth factor receptor)
Diseases named in the same sentence as EGFR in open-access papers (continued):
Sharing a sentence is not in itself a finding about the gene and the disease.
lung cancer (continued). "Our findings are in line with findings showing that EGFr inhibitors reduce phosphorylation of EGFr in lung cancer cell lines." (PMID 29508172, 2018). "The EGF-induced endocytic degradation of EGFR was examined in a panel of lung cancer cells using immunoblotting." (PMID 29976202, 2018). "Phase 1 clinical trials of osimertinib demonstrated a response rate of 61% and a disease control rate of 95% in advanced lung cancer patients with prevailing cancer progression after EGFR TKI treatment." (PMID 29973561, 2018). "Patients being treated with EGFR inhibitors will require continual assessment of progression of lung cancer in order to study how these patients become resistant to therapy and to develop strategies to prevent resistance." (PMID 29973561, 2018). "First, we showed that GNA potentiated the inhibitory effect of erlotinib on lung cancer cell proliferation, colony formation, tumor growth, and EGFR phosphorylation, which correlated with the inhibition of cMet activity." (PMID 29449529, 2018). "These HKGs have low expression variation compared to current lung cancer markers (e.g., EGFR, KRAS) and were involved in the most common biological processes (e.g., metabolism, stress response)." (PMID 29761043, 2018). "In nonsmall cell lung cancer (NSCLC), the EGFR V843I mutation and MET amplification were described as resistance‐supporting in afatinib therapy." (PMID 29325228, 2018). "Overexpression of EGFR and its ligands is present in a variety of epithelial tumor cells such as lung cancer, breast cancer, bladder cancer, prostate cancer and squamous cell carcinoma of the head and neck." (PMID 29455664, 2018). "This study suggests that cotargeting EGFR and YAP is an effective strategy in EGFR mutant lung cancer." (PMID 29321482, 2018). "Previous studies have demonstrated that EGFR, a well-known oncogenic driver, contributes to the initiation and progression of lung cancer." (PMID 29300342, 2018). "EGFR-TKI have been used as a first-line treatment against lung cancer, but the increasing occurrence of drug resistance and the associated adverse sides precludes it widespread application." (PMID 30555330, 2018). "Many retrospective studies in colon and lung cancers have demonstrated poor clinical outcomes as a result of treatment with EGFR tyrosine kinase inhibitors in patients harbouring KRAS mutations." (PMID 28445400, 2017). "In lung cancer, a tight cooperation between the EGF/EGFR and mPGES-1 causes an enhanced tumorigenisis." (PMID 29246166, 2017). "Several studies implicate that lung cancer progression is governed by the interaction between epidermal growth factor receptor (EGFR) signaling and protein kinase C (PKC) pathways." (PMID 28399187, 2017). "EGFR is highly expressed in lung cancer, and we were able to determine the effect of VJ treatment on the EGFR activation on both cell lines." (PMID 29234489, 2017). "A number of third-generation TKIs are in clinical development, and osimertinib has been approved by the US Food and Drug Administration for the treatment of patients with EGFR T790M mutant lung cancer after failure of initial EGFR kinase therapy." (PMID 28620581, 2017). "EGFR-independent SRC is also activated in other EGFR-TKI-resistant lung cancer cells, and dasatinib together with EGFR-TKIs overcomes drug resistance." (PMID 29050315, 2017). "To investigate the molecular mechanism of CSCs in EGFR-positive lung cancer, we first examined the expression of EGFR in three lung cancer cell lines, namely HCC827, A549, and H520." (PMID 28787001, 2017).
lung cancer (continued). "Whereas ZEB1 promoted growth in KRAS-mutated lung cancer cells, ZEB1 expression suppressed cell growth in EGFR-mutated lung cancer cells." (PMID 28587302, 2017). "In the advanced setting, options for first-line treatment of EGFR-positive lung cancer include first-generation TKIs (erlotinib, gefitinib) and afatinib, a second-generation kinase inhibitor." (PMID 28620581, 2017). "Liquid biopsies are considered important because genetic information from tumors can determine responses to certain treatments, such as epidermal growth factor receptor tyrosine kinase inhibitor (EGFR-TKI) in lung cancer." (PMID 28099915, 2017). "Lung cancer in non-smokers has many unique clinical, pathological and genetic features, which include dominant adenocarcinoma subtype, more frequent in women, higher frequency of EGFR and EML4-ALK mutations, and family history of lung cancer." (PMID 29137177, 2017). "We then investigated the mechanistic basis for Met to “sensitize” EGFR WT lung cancer cells to the inhibitory effect of Erlo." (PMID 29312591, 2017). "For example, the role of EGFR in non–small cell lung cancer and multiple cancer types are evaluated." (PMID 29511483, 2017). "For instance, stem cell population in lung cancer cells were shown to be relatively resistant to gefitinib, a tyrosine kinase inhibitor showing specificity to the epidermal growth factor receptor (EGFR)." (PMID 29143801, 2017). "It was initially developed because improper activation of EGFR signaling appears frequently in lung cancer, thus, ASCO guidelines recommended GEF for the treatment of advanced NSCLC in second- or third-line settings." (PMID 28961023, 2017). "This was responsible for failure of the first generation TKIs, gefitinib or erlotinib in lung cancer patients with wild type EGFR in earlier clinical trials." (PMID 28881608, 2017). "According to comprehensive reviews a generally high but variable (61-100%) concordance for driver mutations (EGFR and KRAS) between primary tumours and metastases has been reported for lung cancer." (PMID 28347348, 2017). "Recent studies showed that CX4945 induced down-regulation of the autophagosome-mediated EGFR in lung cancer, while EGFR inhibitors induced, in lung adenocarcinoma, activation of the HGF/Met pathway as a mechanism of drug resistance." (PMID 28873435, 2017). "In this study, we showed that one of the major challenges of EGFR TKI-resistant lung cancer treatment can be overcome by MnO2 NPs, which are effective at reducing GSH levels." (PMID 29255705, 2017). "Clinical trials have revealed that treatment of advanced EGFR lung cancers is superior to chemotherapy, using the appropriate TKIs." (PMID 28430586, 2017). "Inspired by these successful recent cases, in this study we further improved the computational and experimental workflow to search for T790M-mutant EGFR inhibitors, which we believe will likely constitute a novel treatment of EGFR TKI-resistant lung cancer." (PMID 29238696, 2017). "The study identified a decreased GAS5 expression in lung AD tissues and in lung AD cells A549, and H1299 EGFR-wild-type, as well as EGFR-mutated H1975 (T790 M) and HCC827 (E746-A750 deletion) lung cancer cell lines." (PMID 28904641, 2017). "It was also noted that EGFR mutant lung cancer cell lines selectively activate AKT and STAT3 signaling pathways, promoting cell survival." (PMID 28521301, 2017). "The studies mainly focused on EGFR and related biomarkers in lung cancers in the studies comparing the molecular status between primary cancers and matched metastases." (PMID 29312572, 2017). "As a member of the Erb family of receptor tyrosine kinases, the epidermal growth factor receptor (EGFR) protein plays a key role in the carcinogenesis of lung cancer." (PMID 29238696, 2017). "On the other hand, phosphorylation of EPHA2 promotes SRC activation and is involved in the acquisition of resistance of lung cancer cells to EGFR-TKIs." (PMID 29050315, 2017).
lung cancer (continued). "EGFR-TKI combined with chemotherapy as a new strategy has become a hot research topic in the treatment of lung cancer." (PMID 29371987, 2017). "During the last 15 years, pharmacogenomics of lung cancer have established targeted therapy with tyrosine kinase inhibitors (TKIs) for epidermal growth factor receptor (EGFR) positive patients in adenocarcinoma or mixed adenosquamus lung cancer patients." (PMID 28101783, 2017). "Some studies have shown that the expression of the metastasis-promoting gene JAG1 in lung cancer cells depends on activation by EGFR." (PMID 28628609, 2017). "Computed tomography (CT) is wildly used in clinic to evaluate lung cancer patients and few studies have been carried out to investigate the imaging features of ADC with EGFR mutations." (PMID 28949965, 2017). "In the current study, we demonstrate, for the first time, that ING5 knockdown promotes invasion of lung cancer cells by inducing EMT via EGFR/PI3K/Akt and IL-6/STAT3 signaling pathways." (PMID 28903339, 2017). "A proximity ligation assay (PLA) was applied to detect EGFR homodimers in non–small cell lung cancer (NSCLC) cell lines and tissue specimens." (PMID 29069773, 2017). "YAP1 has been identified as a key determinant to enhance treatment sensitivity to EGFR-targeted therapy in lung cancer." (PMID 29163769, 2017). "Overall, smoking status was the most significant factor for the presence of the EGFR and KRAS mutations in lung cancer." (PMID 28881771, 2017). "Unlike ALK, there are several mechanisms of resistance that have been reported in EGFR-expressing lung cancer cells and BCR-ABL (breakpoint cluster region-abelson)-expressing chronic myeloid leukemia (CML) cells." (PMID 29143801, 2017). "Taken together, our findings uncover a novel mechanism that EGFR directly modulates MUFA synthesis to promote lung cancer growth." (PMID 28724430, 2017). "Although the KRAS mutation, which resulted in EGFR-independent ERK activation, was suggested to be a potential biomarker for predicting the efficacy of EGFR TKI in lung cancer, it was rare in HNSCC." (PMID 28134774, 2017). "In the recently reported AURA3 trial, plasma EGFR T790M status independently predicted improved outcomes for patients with EGFR mutant lung cancers who received osimertinib versus platinum/pemetrexed chemotherapy." (PMID 28392802, 2017). "EGFR overexpression is typical of tumors of epithelial origin, such as breast, colorectal, and lung cancer." (PMID 29271876, 2017). "The reduced EGFR and Ki67 expression in the implanted tumors further supported that miR-370 over-expression inhibited proliferation of lung cancer cells in vitro." (PMID 29152147, 2017). "Second, previous reports show that EGFR is overexpressed and abnormally activated in lung cancers, and that exogenous BDNF increases TrkB activation and affects cancer cell signaling." (PMID 29312608, 2017). "We found that miR-370 acted as a tumor suppressor to reduce EGFR expression and inhibited the growth and metastasis of lung cancers by down-regulating the ERK1/2 and AKT signaling." (PMID 29152147, 2017). "In that study, we found that only 22% of lung cancer patients eligible for EGFR testing (based on their histologic classification and stage) received the test." (PMID 28558785, 2017). "The lung cancer cell lines included in this study were PC-9 (EGFR exon 19del), PC-9ER (EGFR exon 19del + T790M), and H1975 (EGFR L858R + T790M)." (PMID 29285266, 2017).
lung cancer (continued). "Targeting these EGFR mutations that are related to lung cancer, EFIRM was able to accomplish an astounding sensitivity and specificity of over 95% in a cohort of lung cancer patients, distinguishing the genetic makeup of cancers from a biofluid sample." (PMID 28443278, 2017). "The identification of activated forms of the epidermal growth factor receptor (EGFR) as oncogenic drivers in non–small cell lung cancer (NSCLC) has rendered this receptor a key target in precision medicine." (PMID 29069773, 2017). "Induction of miR-370 over-expression attenuated the EGFR expression while inhibition of endogenous miR-370 expression by transfection with miR-370 inhibitor increased the EGFR expression in lung cancer cells." (PMID 29152147, 2017). "We firstly compared the EGFR expression level in PC-10 and SCC-015 with that in an EGFR-overexpressing lung cancer A431 cell line and in a normal lung-derived TIG-3 cell line." (PMID 28642617, 2017). "However, our results are consistent with clinical findings that showed poorer response rates of PD-1/PD-L1 targeting agents in lung cancer patients with EGFR mutations, and may explain at least part of the reasons for the lower efficacy of these agents in these specific patients." (PMID 29119113, 2017). "In the context of EGFR TKI acquired resistance, the clinical efficacy of dacomitinib in patients with EGFR-mutant lung cancers progressing on first-generation EGFR TKIs that were included in these trials was disappointingly low, with an overall RR of about 8%." (PMID 28424775, 2017). "(DNal-Cys-Tyr-DTrp-Lys-Val-Cys-Nal)NH2, blocked BA1-induced EGFR or ERK tyrosine phosphorylation in lung cancer cells and diminished clonal growth of NCI-H1299-BRS-3 cells." (PMID 29262666, 2017). "In this study we have demonstrated that the responses to MET inhibition in an in vitro and in vivo lung cancer model differed depending on the EGFR genotype." (PMID 28141869, 2017). "Examining lung cancer patients (n = 65) with EGFR T790M who received 3rd generation EGFR-TKI, we find that the Kaplan-Meier curves for progression-free survival do not show significant differences between the low VAF cases (≤5%) and the high VAF cases (>5%)." (PMID 29123093, 2017). "Next, the levels of KRAS and EGFR mutations in the plasma were determined in the 52 patients (36 with EFGR L858R mutation and 16 with KRAS exon 2 mutation) with early stage lung cancer before surgery (day zero)." (PMID 28382702, 2017). "After multiple-testing correction, 112 SNPs in eight genes (ATR, EGFR, MET, PIK3R1, PIK3R3, PTPN2, STAT3, and STAT5A) remained significantly associated with lung cancer risk with FDR <0.20." (PMID 28400551, 2017). "Because it was observed that TKIs induced drug resistance in EGFR mutant lung cancer, this indicates that genetic variation and tumor heterogeneity can act as intrinsic drivers for the acquisition of additional mutations upon drug treatment." (PMID 27757846, 2017). "Based on the observations that Met and Erlo additively inhibited the growth of EGFR WT A549 lung cancer cells in vitro, we examined the therapeutic effect of these two agents on the growth of xenograft tumors in immuno-compromised mice." (PMID 29312591, 2017). "Epidermal growth factor receptor (EGFR) is often overexpressed or mutated in a variety of cancers, like lung cancer and colorectal cancer, and this leads to enhanced activation and tumorigenesis." (PMID 27903975, 2017). "Together, these evidences prove that lung cancer growth is more dependent on SCD1 enzyme activity when EGFR is activated." (PMID 28724430, 2017). "In current clinical trials of lung cancer immune checkpoint blockade treatment, patients with ALK fusion and EGFR mutation have shown minimal responses." (PMID 29189709, 2017).
lung cancer (continued). "The demonstration of these associations with treatment and survival outcomes provides evidence of the clinical utility of the RT-PCR and MS tests for predicting the prognosis and clinical benefits of EGFR-TKI treatment in patients with lung cancer." (PMID 29254176, 2017). "Recent evidence has shown aberrant expression of EGFR in most human malignancies, such as lung cancer and breast cancer." (PMID 28352075, 2017). "Most illustrative of this point is the existence of EGFR mutations which determine both dependence on EGFR signaling and responses to EGFR inhibitors in patients with lung cancer." (PMID 28532501, 2017). "Our study suggests a pathway differs from mTOR cascade in that EGFRhigh lung cancer cells survive Met with sustained phosphorylation of EGFR in response to EGF, and increased sensitivity to Erlo, one of the most wildly used EGFR-TKIs at present in the clinic." (PMID 29312591, 2017). "Targeted therapy with epidermal growth factor receptor-tyrosine kinase inhibitors (EGFR-TKIs) have benefited many lung cancer patients, but they still suffer from drug resistance and compatibility." (PMID 28212270, 2017). "The clones were also highly sensitive to the 3rd-generation EGFR TKI AZD9291, which is cytotoxic to lung cancer cells with EGFR T790M." (PMID 28422737, 2017). "In a different study, EGFR-targeted chitosan nanoparticles successfully delivered a combination of cisplatin and Mad2 siRNA in cisplatin-sensitive and -resistant in vivo lung cancer models." (PMID 28290155, 2017). "In the present study we have generated 2D and 3D lung cancer models and analyzed their sensitivities towards broad-spectrum cytotoxic agents or targeted inhibitors of the EGFR pathway." (PMID 29296175, 2017). "According to the chi-square test and the t-test, gender, age, smoke history, lung cancer history, bone metastasis, pathology, and mean blood pressure were significantly different between the YC and YH groups, as well as the EGFR gene status." (PMID 28203260, 2017). "The result of this study, however, indicated that mutant EGFR in lung cancer cells prompted the destruction of bone lesions, leading to higher risk of SREs." (PMID 29113396, 2017). "The characteristics of this cell line were compared to those of PC9-G lung cancer cells with EGFR T790M generated by continuous exposure to gefitinib." (PMID 28422737, 2017). "For the first time, this nationwide population-based study showed the benefit of statin use in patients with lung cancer receiving EGFR-TKI therapy." (PMID 28158206, 2017). "EGFR is frequently overexpressed in approximately 40–80% of NSCLC tumors; therefore, EGFR activity and/or expression is an important factor in the treatment of lung cancer that must be taken into consideration by clinicians attempting to manage the disease." (PMID 29132432, 2017). "The discovery of oncogenic mutations in the tyrosine kinase (TK) domain of the epidermal growth factor receptor (EGFR) gene, and sensitivity of mutant lung cancers to EGFR-TK inhibitors (TKIs), have revolutionized the treatment of advanced NSCLC." (PMID 28915692, 2017). "Dedifferentiation from adenocarcinoma to small-cell carcinoma is also recognized in EGFR-mutant lung cancer." (PMID 28487881, 2017). "A number of institutions worldwide have integrated EGFR molecular profiling into routine lung cancer diagnosis to personalize treatment decisions, and especially the use of TKIs." (PMID 28881604, 2017). "While patients with EGFR- and ALK-mutant lung cancer do often respond to EGFR and ALK inhibitors, these responses are temporary, as acquired resistance inevitably develops." (PMID 28145866, 2017). "The EGFR signaling network plays a significant role in the epithelial tissues maintenance and growth, active EGFR signaling is frequently observed in lung cancer, and EGFR level is related with advanced stage of disease and bad prognosis." (PMID 28430586, 2017).